DSC2 (desmocollin 2)
Diseases named in the same sentence as DSC2 in open-access papers (continued):
Sharing a sentence is not in itself a finding about the gene and the disease.
heart disease (3 papers, 2021 to 2025). "A substantial number of genetic variants in the genes DSP, JUP, DSC2, KLHL24 and GJA1 have been reported to underly skin and/or cardiac disease." (PMID 36142674, 2022). "One of these studies additionally showed that gradual knockdown of DSC2 resulted in dose-dependent cardiac disease severity." (PMID 36142674, 2022). "In CMs, we found three genes in OMIM (Online Mendelian Inheritance in Man) with gene × treatment interactions that are known to cause Mendelian forms of heart disease: PSMA6, AARS2, DSC2." (PMID 33988505, 2021). "Mutations in desmosomal genes have been observed in 50% of patients with arrhythmogenic heart disease, and these are represented by mutations in the genes for Plakophilin C (PKP2), Desmoplakin (DSP), Desmocollin-2 (DSC2), Desmoglein-2 (DSG2), and Plakoglobin (JUP)." (PMID 40361967, 2025).
bacterial infection (1 paper, 2025). "When comparing gene expression in viral versus bacterial infection, five classifier genes (OAS3, IFI27, USP18, DSC2, RSP21) were significantly differentially expressed." (PMID 41496780, 2025).
DSC2 also shares sentences with these, for which no sentence is quoted: hypertrophic cardiomyopathy (4 papers); catecholaminergic polymorphic ventricular tachycardia (2); Long QT syndrome (2); Naxos disease (2); oral squamous cell carcinoma (2); squamous carcinomas (2); adenoma (1); alcoholism (1); amyloidosis (1); ankylosis (1); Behçet's disease (1); breast invasive carcinoma (1); Brugada syndrome (1); carcinoid tumor (1); channelopathy of (1); dermatitis (1); eczema (1); endometrial cancer (1); familial thoracic aortic aneurysms and dissections (1); genetic disease (1); gram-positive bacterial infections (1); hereditary cancer syndrome (1); hereditary colorectal cancer (1); hereditary hypotrichosis simplex (1); hyperthyroidism (1); hypothyroidism (1); ichthyosis (1); kidney (1); kidney cancer (1); left ventricular noncompaction (1).
A further 26 diseases each share a sentence with DSC2 in 1 paper.